RNU7-8P (RNA, U7 small nuclear 8 pseudogene)
Synonyms: U7.8; RNU7-139P
Gene: Small nuclear RNA gene on chromosome 1 (77,420,325 to 77,420,386, forward strand). Ensembl gene ENSG00000251767.
Homologues: Orthologues: macaque U7 (98% identical). Paralogues in human: RNU7-13P (95% identical), RNU7-18P (92% identical), RNU7-28P (92% identical), RNU7-11P (90% identical), RNU7-26P (90% identical), RNU7-2P (90% identical), RNU7-3P (90% identical), RNU7-41P (90% identical), RNU7-4P (90% identical), RNU7-6P (90% identical), RNU7-14P (89% identical), RNU7-22P (89% identical), and 142 more.
Diseases named in the same sentence as RNU7-8P in open-access papers:
RNU7-8P is named in the same sentence as 1 disease in open-access papers, as found by Europe PMC text mining. Sharing a sentence is not in itself a finding about the gene and the disease.
RNU7-8P shares sentences with these, for which no sentence is quoted: infection (1 paper).